ENSG00000285635 (novel transcript)
Gene: Protein-coding gene on chromosome 3 (98,521,133 to 98,585,498, reverse strand). Ensembl gene ENSG00000285635.
Genetic constraint (gnomAD): Missense variants: 42 observed, 61.7 expected, observed/expected ratio (o/e) 0.68, 90% interval 0.53 to 0.88. Synonymous variants: 24 observed, 22.86 expected, observed/expected ratio (o/e) 1.05, 90% interval 0.76 to 1.48.